INS (insulin)
Diseases named in the same sentence as INS in open-access papers (continued):
Sharing a sentence is not in itself a finding about the gene and the disease.
diabetes (continued). "Diabetes mellitus (DM) is one of the most widely occurring metabolic disorders throughout the world which is characterized by chronic hyperglycemia as a result of insulin resistance or defect in insulin secretion." (PMID 23176672, 2012). "The most commonly applied models of diabetes involve STZ treatment that evoke compromised glycemic homeostasis and thus represent a model of type 1 diabetes resulting from decreased insulin secretion due to gradual pancreatic beta-cell death." (PMID 22993483, 2012). "Mechanisms proposed to link diabetes and thyroid cancer include elevated TSH, insulin, glucose, triglycerides, insulin resistance, obesity, vitamin D deficiency, and antidiabetic medications." (PMID 22778714, 2012). "In case of diabetes, high diacylglycerols activates PKC, which further activates serine/threonine kinases and inhibits insulin signaling." (PMID 22891067, 2012). "Our data indicated that encapsulated propolis can inhibit the increase of fasting serum glucose, modulate lipid metabolism as well as improve the insulin sensitivity in T2DM rat and, therefore, to delay the development of diabetes." (PMID 21716678, 2012). "We therefore conducted the DAWN (Diabetes Attitudes, Wishes and Needs) JAPAN study in an attempt to identify specific patient- and physician-related factors which contribute to delay of insulin initiation among Japanese patients with diabetes." (PMID 22719830, 2012). "Our study was focused on pancreatic ß-cells because HNF4α is one of the culprit gene products for a dominantly inherited form of diabetes, MODY, mainly characterized by the defect in insulin secretion from ß-cells." (PMID 22952853, 2012). "In contrast, type 2 diabetes, or non-insulin-dependent diabetes mellitus (NIDDM), involves progressive insulin resistance as target tissues become insensitive to insulin resulting in chronic hyperglycemia and hyperinsulinemia." (PMID 22489274, 2012). "Sustained reversion of diabetes mediated by hBMSCs-VEGF was secondary to endogenous β-cell regeneration and correlated with activation of the insulin/IGF receptor signaling pathway involved in maintaining β-cell mass and function." (PMID 22879915, 2012). "The higher frequency of diabetes in Alström syndrome is explained by the specific role of ALMS1 in β-cell function and/or peripheral insulin signaling pathways, in parallel with adipogenesis impairment." (PMID 22284844, 2012). "However, BACE1 mRNA levels were not significantly affected by STZ treatments in 5XFAD mice, suggesting that transcriptional mechanisms may not account for the BACE1 elevation associated with insulin-deficient diabetes." (PMID 22403710, 2012). "Glucose transporter 4 (GLUT4) is a principal glucose transporter in response to insulin, and impaired translocation or decreased expression of GLUT4 is believed to be one of the major pathological features of type 2 diabetes mellitus (T2DM)." (PMID 22384078, 2012). "Diabetes mellitus (DM) is a chronic disorder characterized by hyperglycemia, with disturbances in carbohydrate, lipid, and lipoprotein metabolism stemming from defects in insulin secretion and insulin action, or both." (PMID 22969823, 2012). "In keeping with this, some studies have suggested that there may be an association between insulin sensitivity and arterial stiffness in individuals without diabetes, as well as in young healthy women, diabetic adults, and in nondiabetic hypertensive older adults." (PMID 23028545, 2012). "Another study focused on acute asthma at the Central Hospital in Maputo and the Rapid Assessment Protocol for Insulin Access (RAPIA) was carried out in three provinces of Mozambique to assess problems with providing care and access to medicines for diabetes." (PMID 23171496, 2012). "TZDs are widely used as PPAR-γ agonists in the treatment of diabetes, and TZD-mediated activation of PPAR-γ results in marked improvement in blood glucose levels and insulin sensitivity." (PMID 22969823, 2012).
diabetes (continued). "Diabetes mellitus (DM) is a chronic disease characterized by an increased concentration of glucose in the blood, that occurs when the pancreas does not produce enough insulin or when the body cannot effectively use the insulin it produces." (PMID 23049626, 2012). "Type 1 diabetes mellitus (T1DM) results from the autoimmune destruction of the insulin-producing beta cells by localized inflammation around the pancreatic islets involving cytotoxic T cells anti-islet antibodies, and antigen presenting cells." (PMID 23144715, 2012). "Data on both prescribed and dispensed insulin and oral medication for diabetes suggested an underestimation of prevalence data from HUNT3, as a substantial number with diabetes also are treated with life style only." (PMID 22978749, 2012). "Since streptozotocin-induced diabetes is accompanied by insulin resistance, EEM improved insulin sensitivity." (PMID 22474494, 2012). "Compared to the diabetes by glucose, patients by HbA1c were generally older, and had higher BMI, waist circumference, blood pressure, lipids (except for HDL-cholesterol) and insulin levels." (PMID 22615957, 2012). "Type 1 diabetes, also known as insulin-dependent diabetes mellitus (IDDM), typically results from autoimmune destruction of pancreatic islet cells responsible for insulin secretion within the first few decades of life." (PMID 22489274, 2012). "Type 2 diabetes mellitus (T2DM) is the most common human endocrine disease and is characterized by peripheral insulin resistance and pancreatic islet β-cell failure." (PMID 22110477, 2012). "The comparative proteomic analysis of mitochondria from insulin-sensitive versus insulin-resistant vastus lateralis muscle suggests an altered density of key enzymes involved in fat oxidation which might be an important contributory aspect of lipid accumulation in diabetes." (PMID 22523676, 2012). "Their potent effects on improving glucose disposal, insulin sensitivity, plasma lipid parameters, and on inducing body weight loss are very similar between these two endocrine FGFs and have been reported in multiple models of diabetes and obesity in rodents and non-human primates." (PMID 22457778, 2012). "Salsalate on the other hand is a very interesting drug in the context of diabetes and has been shown to reduce CRP, FFA, and triglycerides while increasing insulin sensitivity and adiponectin levels." (PMID 23087692, 2012). "The OA-DKQ assesses diabetes-related knowledge whilst the MDKT assesses general diabetes knowledge and insulin use." (PMID 22361093, 2012). "The hyperlipidemia associated with diabetes may result from an accelerated hepatic triglyceride biosynthesis and the release of VLDL without an increase in its rate of clearance from the blood by lipoprotein lipase, which is dependent on the insulin/glucagon ratio." (PMID 23190471, 2012). "Additionally, individual food groups and components of the diet, such as monounsaturated fatty acids, fruits, vegetables, and whole grain cereals may protect against the development of diabetes, possibly through the amelioration of insulin sensitivity and their anti-inflammatory actions." (PMID 23270372, 2012). "However, manipulation of postprandial glucose by nateglinide – which stimulates insulin release – was unable to reduce diabetes incidence (NAVIGATOR trial), suggesting that the mechanisms of action for reducing postprandial glucose may be a determinant of the final effect." (PMID 22780564, 2012). "Diabetes leads to increase of fast blood sugar (FBS) and HbA1c, and decrease of β-cell number and insulin." (PMID 25653767, 2012). "Comparison with previously identified dietary obesity and diabetes-related QTL revealed QTL with effects on liver weight in the NAFLD4 and NAFLD11 support interval and for serum insulin and serum glucose within NAFLD14." (PMID 22973538, 2012).
diabetes (continued). "This study demonstrated short term treatment of people with diabetes with an MMPI resulted in decreased inflammation and improved insulin sensitivity." (PMID 23025537, 2012). "We measured serum amylase, plasma insulin, obesity-related parameters such as leptin, cardiometabolic risk factors, and anthropometric parameters in a cross-sectional study of 54 asymptomatic subjects (mean age 48.6 ± 7.6 years) who were not being treated for diabetes." (PMID 22748134, 2012). "In animal models of diabetes as well as in human type 2 diabetes, a down-regulation of AKT/mTOR signaling indicates impaired insulin signaling." (PMID 22969728, 2012). "It down-regulated not only the level of blood glucose and plasma insulin but also the expression level of leptin and TNF-α mRNAs in white adipose tissue of the diabetes/obesity mouse KK-Ay." (PMID 23675258, 2012). "United Kingdom Prospective Diabetes Study (UKPDS) has demonstrated the progressive nature of T2DM, and as disease progresses, a combination agents—oral antidiabetic drugs (OAD) and insulin—are needed in order to maintain good sugar control." (PMID 22645689, 2012). "GIP has a potent stimulatory effect on insulin release from the pancreas, but several experimental studies have demonstrated that GIP looses this action in diabetes because GIP-R in pancreatic islets are substantially down-regulated in a hyperglycemic state." (PMID 22973260, 2012). "The insulin signaling cascade in the muscle was evaluated in 26 morbid obese patients with NAFLD, of whom 43% had NASH, 59% insulin resistance and 26% type 2 diabetes mellitus." (PMID 22359625, 2012). "To evaluate the possible contribution of hBMSCs-VEGF to the recovery of β-cells and whether the reversion of diabetes was secondary to a direct differentiation of hBMSCs to β-cells or secondary to endogenous β-cell regeneration, we measured both mouse and human serum insulin." (PMID 22879915, 2012). "In beta-cells, ghrelin treatment has been shown to increase expression of insulin and PDX1, as well as beta-cell replication in a diabetes model." (PMID 22577380, 2012). "TZDs also reduce serum lipid levels in rodents and humans suffering from non-insulin-dependent diabetes mellitus (NIDDM), which reduce plasma triglyceride, fatty acid, and insulin levels and increase HDL cholesterol levels." (PMID 22919315, 2012). "Transgenic expression of IL-4 in β cells under the control of the insulin promoter in NOD mice suppresses insulitis and diabetes; however, islet expression of IL-4 is incapable of preventing islet rejection in diabetic recipients." (PMID 22690214, 2012). "Diabetes was induced by a combination of HFD and a single low dose Streptozotocin (STZ) injection, which is toxic to insulin-producing beta cells." (PMID 22761194, 2012). "Finally, the effect of incretins on insulin secretion, which is now highlighted in the context of treatment of diabetes and bariatric surgery, could be a powerful tool for decreasing postprandial glucose and for preventing diabetes." (PMID 22780564, 2012). "Type 1 diabetes mellitus (T1DM) is an autoimmune disorder in which cytotoxic T lymphocytes identify and destroy insulin producing beta cells in the pancreas." (PMID 23144715, 2012). "Type 2 Diabetes Mellitus (T2DM) is characterized by chronic hyperglycemia with disturbance in carbohydrate, lipid, and protein metabolism due to insulin resistance and beta cell dysfunction." (PMID 22645689, 2012). "The lower S-Urate at baseline in type 2 diabetes compared with non-diabetes and the inverse relation between changes in S-Urate and S-Glu in type 2 diabetes in our study could be explained by an increased resorption in proximal tubule and both insulin and S-Glu are involved in this regulation." (PMID 22192330, 2011). "In an animal model of type 2 diabetes mellitus, the sand rat Psammomys obesus, it has been shown that SELS (tanis) is expressed in the liver in inverse proportion to circulating glucose and insulin levels." (PMID 20619427, 2011).
diabetes (continued). "Type 2 diabetes mellitus (T2DM) is a chronic metabolic disorder that results from defects in both insulin secretion and insulin action." (PMID 22174657, 2011). "As dyslipidemia is one of the important components of diabetes and insulin resistance, the reductions of blood lipids, in particular triacylglycerols by BBR, are beneficial to insulin sensitivity and glucose utilization in the peripheral tissues." (PMID 22363882, 2011). "Remarkably, high numbers 33 to 90% of ductal cells were found to be insulin positive, and 17% to 95% of the ducts harboured insulin-positive cells in SPK patients with recurrent autoimmunity and diabetes." (PMID 22007286, 2011). "Furthermore, we evaluated the impact of these variants on diabetes-related intermediate traits in the Inter99 cohort where study participants have been characterized by an oral glucose tolerance test (OGTT) and derived estimates of insulin release and insulin sensitivity." (PMID 21283750, 2011). "Additionally, the authors did not evaluate whether specific diabetes treatments, such as insulin, had any effect on the risk of IHD and CVA." (PMID 21978180, 2011). "The inverse correlation between insulin and CBG has also been observed in small clinical studies and upregulation of CBG has been proposed as a marker of type 1 diabetes mellitus." (PMID 21750736, 2011). "Diabetes studies and epidemiological studies on glucose tolerance have frequently used HOMA, and recent reports have shown its value for assessment of insulin sensitivity in the critically ill." (PMID 21276273, 2011). "The research done in the Diabetes Control and Complications Trial (DCCT) showed that exogenous insulin administration leading to tight glycemic control resulted in decreased incidence and progression of diabetic retinopathy." (PMID 21293735, 2011). "Although glibenclamide lowers plasma glucose level, mainly by stimulating insulin secretion from pancreatic β-cells, destruction of β-cells are observed in STZ-induced diabetes model (type 1 diabetes)." (PMID 21603234, 2011). "Understanding the mechanism of IR and IGF-1R activation is critical for the future design of insulin mimetics and inhibitors of IGF action for the treatment of diseases such as diabetes and cancer." (PMID 22140443, 2011). "This is the first time to report that the upregulation of insulin signaling proteins (IRS-1 and AKT-2) was obtained in a STZ-induced diabetic rat under ICT by EA." (PMID 21754922, 2011). "In the Diabetes Control and Complications Trail (DCCT), experimental intense insulin therapy produced less decline in stimulated C-peptide values." (PMID 27713291, 2010). "Generally, the serum glucose concentration in patients with diabetes mellitus (DM) was easy to be increased, yet it could be controlled to a satisfactory level with the adjustment of insulin administration." (PMID 21187862, 2010). "Insulin and leptin are important central signals to regulate PFC functions, and these central actions are attenuated in both obesity and diabetes." (PMID 20181219, 2010). "Insulin dependent diabetes mellitus (IDDM) is the second most common chronic disease of childhood believed to be autoimmune in nature and characterized by irreversible destruction of insulin-secreting pancreatic β islet cells." (PMID 21197448, 2010). "Oral glucose tolerance tests (OGTTs), are a mainstay for assessing insulin sensitivity in the non-invasive diagnosis of impaired glucose tolerance (IGT) and diabetes mellitus." (PMID 20507559, 2010). "Onset of diabetes in SDT fatty rat is accelerated to 5 weeks of age by developing adiposity and insulin resistance." (PMID 20508774, 2010). "Since the Diabetes Control and Complications Trial (DCCT) showed that tighter control reduces complication rates, there has been more emphasis on intensified insulin therapy." (PMID 20633252, 2010).
diabetes (continued). "In all, clinical studies indicate that adult patients, with type 1 diabetes mellitus, are favoured by CSII treatment in comparison to MDI therapy and are led to a better glycaemic control with less hypoglycaemic episodes and insulin requirements." (PMID 20589066, 2010). "Insulin-sensitising drugs, such as RSG, are widely used in clinical practice to improve diabetes alteration in glucose metabolism." (PMID 20953342, 2010). "This includes in its definition, the presence of diabetes, the metabolic syndrome, and levels of ALT, AST and fasting insulin." (PMID 20529259, 2010). "Diabetes is an obligate feature of WRS, by definition, and it is permanent and totally insulin-dependent from the onset." (PMID 21050479, 2010). "The consequences for β cells, resulting in diabetes in WRS patients, appear to affect principally the proliferation and differentiation of the cells, as well as proinsulin trafficking and insulin secretion." (PMID 21050479, 2010). "When looking at the insulin sensitivity indexes, we, as expected, observed a lower HOMA-beta but a higher HOMA-IR in diabetes cases than that in the controls." (PMID 20811623, 2010). "Type 2 diabetes mellitus (T2DM) is a disorder characterized by both insulin resistance and impaired insulin secretion." (PMID 20369014, 2010). "Type 2 diabetes mellitus (T2DM) is characterized by insulin resistance in insulin target tissues, and impaired insulin secretion from pancreatic β cells." (PMID 20300528, 2010). "Serum FGF-21 levels correlated positively with triglycerides, fasting blood glucose, apolipoprotein B100, insulin and HOMA-IR but negatively with HDL-C and apolipoprotein A1 after adjusting for BMI, diabetes and hypertension." (PMID 21206918, 2010). "The more prevalent form of diabetes is Type- 2 (NIDDM), a condition which often develops over a period of time, involves reduced responsiveness of tissues to circulating insulin, and is often controlled by diet or oral hypoglycemic drugs." (PMID 20922079, 2010). "Furthermore the study aimed at determining whether mutations in KCNJ11, ABCC8, HNF1A, HNF4A or INS are common in AAB negative diabetes." (PMID 20863361, 2010). "Peak glucose and insulin responses occurred in the first 60 min among subjects with NFG and IFG, but at 120 min among subjects with diabetes." (PMID 19476649, 2009). "Thus, defects in both pancreatic beta-cell insulin secretion and peripheral insulin action coexist simultaneously in this knockout mouse model of diabetes, in which activation of compensatory mechanisms to efficiently overcome these metabolic abnormalities may be of vital importance." (PMID 19460132, 2009). "If we express the data in terms of death per thousand patients per year, cardiovascular death in untreated diabetes is 30/1000 versus 11/1000 and 14/1000 in the ACCORD standard and intensive insulin therapy groups, respectively." (PMID 19573240, 2009). "Of the 748 patients included (age 59.7 ± 11.8 years, diabetes duration 11.4 ± 7.3 years, baseline HbA1c 9.1 ± 1.6%), 497 were previously using human neutral protamine Hagedorn (NPH) insulin and 245 analogue basal insulin." (PMID 19504715, 2009). "Insulin treatment lowered NO-IF levels in the OPL and IPL to about half that of the untreated diabetics, however this trend was only statistically significant in the OPL (p=0.01)." (PMID 19936028, 2009). "Subjects with NFG (n = 19), IFG (n = 19), and diabetes (n = 35) had mean ± SEM HOMA2-IR values of 1.0 ± 0.1, 1.6 ± 0.2 and 2.5 ± 0.3 and Matsuda insulin sensitivity index values of 15.6 ± 2.0, 8.8 ± 1.2 and 6.0 ± 0.6, respectively." (PMID 19476649, 2009). "Our patient was treated as a case of type 2 respiratory failure with insulin dependent diabetes mellitus (IDDM) in ICU with antibiotics, bronchodilators, corticosteroids, insulin, and low flow oxygen." (PMID 20442845, 2009). "Most patients with type 2 diabetes mellitus (DM) exhibit tissue insensitivity to insulin." (PMID 19646276, 2009).